MYC (MYC proto-oncogene, bHLH transcription factor)
Diseases named in the same sentence as MYC in open-access papers (continued):
Sharing a sentence is not in itself a finding about the gene and the disease.
tumor (continued). "Silencing or pharmacological inhibition of PIM1 results in MYC-related tumor inactivation, suggesting an essential role of PIM1 for MYC-driven cancer." (PMID 36969025, 2023). "Ectopic MYC expression in malignancies might simultaneously promote aerobic glycolysis and/or oxidative phosphorylation to supply adequate energy and anabolic substrates that are essential for the growth of cells and cell proliferation within the tumor microenvironment." (PMID 37999212, 2023). "GSEA analysis indicated that NOTCH signalling, cell cycle, and MYC targets pathways were commonly upregulated in IKZF1 mutants, suggesting the tumour suppressor function of IKZF1." (PMID 37345307, 2023). "We conclude that introduction of MEK1DD or ER-KRASG12V in addition to expression of MYC and PIK3CAE545K confer tumor initiating ability to early-passage HCK1T/16epi cells." (PMID 36763589, 2023). "However, the relationship between the MYC target gene set and the tumor is unknown." (PMID 37342196, 2023). "The amplification of MYC, CCNE1, and ERBB2 was more frequently detected in CSF than in tumor tissue samples, with detection rates being 46.7% (7/15) vs 26.7% (4/15), 53.3% (8/15) vs 13.3% (2/15), and 26.7% (4/15) vs 13.3% (2/15), respectively." (PMID 37131253, 2023). "Further, a study showed increased sensitivity of MYC-amplified GB models to glycolysis inhibition mediated by NAMPT inhibitor, highlighting a metabolic vulnerability in these tumor subtypes." (PMID 37298093, 2023). "Under oxygenated conditions in the tumor environment, lactate enters the cells via MCT1, stabilizing hypoxia-inducible factor-2α (HIF-2α), and then transactivating c-MYC." (PMID 37190124, 2023). "This gene is transcribed into a long, non-coding RNA involved in tumor formation and regulates long-range chromosomal interactions, including the locus of the MYC oncogene, which maps 500 kb downstream; therefore, it could be speculated that the rearrangement trigger MYC dysregulation." (PMID 38137002, 2023). "Immunohistochemical analyses of harvested tumours confirmed downregulation of NCP26 targets, including MYC, CCND1 and TCF3, and ISR engagement, evidenced by induction of p-GCN2 and DDIT3." (PMID 36631435, 2023). "Our study has uncovered a KDM4B-dependent epigenetic mechanism in the control of tumor progression, providing a rationale for utilizing KDM4B as a promising therapeutic target for the treatment of MYC-amplified GBM." (PMID 38093312, 2023). "Same as CCAT1-S, CCAT1-L is also transcribed from 8q24, 515 kb upstream of c-MYC gene (MYC-515), a tumor type-specific super enhancer region of c-MYC with a length of 150 kb." (PMID 37025163, 2023). "We compared the expression level of six frequently used markers for WNT activation (CTNNB1/beta-catenin, TCF1, TCF4, FZD7, MYC and CCND1) in normal and tumor tissue." (PMID 37149691, 2023). "As a kind of novel marker for malignant tumors, lncRNAs can modulate metabolism-related genes (c-MYC, ASS1, mTORC1), and further exert complex impacts on tumor progression, which expands our understanding of cancer metabolism." (PMID 36969848, 2023). "Tumor growth inhibition reaching 0.5% of control treated SU-DHL-10 xenografts is achieved in vivo and MYC and MCL1 depletion as well as evidence of apoptosis activation after enitociclib treatment is demonstrated." (PMID 37882668, 2023). "The c-MYC oncogene has been reported as a driver gene for malignant conversion of pre-neoplastic liver lesions in human HCC, and for HCC tumor proliferation." (PMID 37627221, 2023). "Amplifications of MYC (four cases), MDM2 (two cases), MDM4 (two cases), and several other genes were identified with the Illumina TruSight Tumor 170 panel in a subset of tumors." (PMID 37891989, 2023). "In TAM, Wnt ligands released from tumor cells can activate the Wnt/β-catenin axis, thereby activating c-MYC, leading to M2 polarization of TAM, which leads to tumor development, migration, and metastasis." (PMID 36721232, 2023).
tumor (continued). "AURKA forms a complex with N-MYC, protecting it from FBW7-mediated degradation, and inhibitors of AURKA disrupt the MYC–AURKA complex, promoting N-MYC degradation and tumor regression." (PMID 37755397, 2023). "Consistent with the c-MYC/Mcl1 prevention model, the AFP immunization also prevented cMet/β-catenin-induced HCC tumor formation (A C, and D, P < 0.05)." (PMID 37040183, 2023). "In terms of molecular mechanism, COMMD proteins in tumor cells regulate the oncogenes of NF-κB, HIF, c-MYC, and others, and are related to signaling pathways including apoptosis, autophagy, and ferroptosis." (PMID 36776284, 2023). "MXD4 is a MAD family protein and putative tumor suppressor that, through heterodimerization with MAX, antagonizes MYC and downstream gene regulatory activities." (PMID 37894362, 2023). "The combination of MYC inhibitors and CAR-T is an effective tumor immunotherapy, but there are still some limitations and challenges." (PMID 36966168, 2023). "The most extensively studied compound directly targeting MYC is Omomyc91, which can potentially damage the MYC/MAX/MXD network and has been demonstrated to trigger tumor regression in a variety of cancer models 92-99." (PMID 37496997, 2023). "In xenograft tumours, GATM knockdown suppressed the expression of MYC, HMGA1, and HMGA2, and GAA diet feeding stimulated their expression." (PMID 37370109, 2023). "The tumor-promoting potential of early- and late-passage HCK1T/16epi expressing the MYC and PIK3CAE545K oncogenes was examined by generating mouse xenografts." (PMID 36763589, 2023). "Various oncogenic pathways, including the c-MYC pathway, are complexly involved in HCC development, leading to high inter- and intra-tumor heterogeneity." (PMID 36746917, 2023). "Comparison of the TAL and RMC populations from the treated tumour revealed a transcriptional switch from high HOXB9 and TFCP2L1 activity in TAL1 cells, to high MYC, HIF1A, YY1 and NFE2L2 activity in RMC cells." (PMID 37236926, 2023). "IHC analysis of Ki-67, MYC, and caspase-3 (CC3) in tumor sections of HD-shSTAT3 and ONS-shSTAT3 xenografts showed that combination treatment suppressed cell proliferation and increased the number of apoptotic cells." (PMID 37190167, 2023). "MYC+MEL cells were increased in LN+AM and expressed high levels of MYC, MITF, SNAI2, and KIT, all of which play crucial roles in tumor progression." (PMID 38065972, 2023). "However, given that cellular metabolism is a complex process involving the activity of numerous genes, we cannot exclude that SHMT2 may also target tumor immunity and tumor progression by affecting the methylation status of mRNAs other than MYC in an m6A-dependent manner." (PMID 37932821, 2023). "Herein, we perform systematic multi-omics characterizations on PKD mice (driven by c-MYC) and ccRCC mice (driven by c-MYC and Setd2 knockout) to investigate SETD2 function in tumor metabolism during PDK-ccRCC transition." (PMID 37989747, 2023). "NANOG also works together with other stemness factors, such as MYC, OCT4, KLF4, SOX2, SOCS2, or ALDH1A1, to control a set of target genes that have important functions in embryonic stem cells and, plausibly, in tumor cells." (PMID 35104240, 2022). "Our current study supports a role for ZNF148 as a tumor suppressor gene in metastatic TNBC, that is actively repressed by MYC." (PMID 36207293, 2022). "In EC, the expression of cancer-promoting genes, MYC, NR5A2, SNAI1, and TWIST1, was found to be significantly higher in tumor-adjacent tissues than in the matched tumors." (PMID 36140779, 2022). "Formonetin inhibits cell proliferation, tube formation, and cell migration and interferes with MYC and STAT3 proteins via the RAS/ERK and JAK1/STAT3 pathways to suppress PD-L1 protein expression thereby promoting tumor cell apoptosis." (PMID 36452480, 2022). "We found that the cells mediating tumor killing (CD8+ T cells, NK cells) had a higher infiltration abundance in the MYC signaling activation group." (PMID 36299592, 2022).
tumor (continued). "Genetic modelling of HCC has indicated that blocking MYC leads to tumour regression, suggesting that HCC can become MYC oncogene-addicted." (PMID 36433941, 2022). "In this Tet-Off inducible MYC model, silencing of MYC expression is achieved by the treatment with doxycycline (DOX), which prevents HCC tumor formation." (PMID 36380966, 2022). "Multiregional analysis across 22 tumour types revealed frequent subclonal focal amplifications in chromosomes 1q (encompassing BCL9 and MCL1), 5p (TERT), 11q (CCND1), 19q (CCNE1) and 8q (MYC)." (PMID 36289203, 2022). "Over 9 years during which the patient received multiple lines of therapy, the tumor maintained BRCA1 LOH, copy number gains in ABCB10/11, high aneuploidy scores (≥13), MYC amplifications (CN ≥ 10) and PARP1 gains (CN = 4)." (PMID 36344544, 2022). "Suppressing Pol II-driven oncogenic transcription, particularly MYC and MYC-dependent transcriptional programs in hematological malignancies, is where BET inhibitors exert their anti-tumor effects." (PMID 36384676, 2022). "Overexpression of CCAT1L increases the expression of MYC and tumour growth, while knockdown of CCAT1 reduces the expression of MYC and inhibits tumour growth." (PMID 35170113, 2022). "Targeted inhibition of ATF4 impedes progression of MYC-driven cancers, emphasizing the important role of this ISR effector in tumor progression." (PMID 36107759, 2022). "Eight registered patients had tumours which were c-MYC amplified, six were HER2 amplified and three were c-MYC and HER2 co-amplified." (PMID 35448150, 2022). "BPTF-silencing impairs cell proliferation and migration in PDA tumours, and strongly enhances the sensitivity to gemcitabine through the downregulation of ABC-transporters in a c-MYC-dependent manner." (PMID 35326669, 2022). "Second, coactivation of NOTCH1 and MYC increases the frequency of NICD1-induced adenoma formation and enables tumor progression and metastases in a mouse model." (PMID 35332121, 2022). "Further, KRAS and c-MYC cooperate to drive an immunosuppressive TME in cancer development, leading to increase in macrophage infiltration of tumours and decrease in CD3+ T cells, B cells and natural killer (NK) cells." (PMID 36483040, 2022). "Nevertheless, CBX8 has been demonstrated to induce tumor growth or progression in CRC and other cancers, and our supplementary experiment indicated that its overexpression induced the protein level of c-MYC." (PMID 35681547, 2022). "The cooperation between MYC and RAS received additional confirmation from experiments in transgenic mice: mice that expressed both MYC and RAS transgenes developed more tumours and with a shorter latency period." (PMID 36176767, 2022). "Combined with our previous studies, berberine can deplete tumor polyamines and inhibit ODC expression, ultimately inhibiting tumor growth, reducing intestinal permeability in CRC patients, and downregulating MYC and HIF1α." (PMID 35912204, 2022). "Eight patients had c-MYC amplified tumours, six were HER2 amplified and three were c-MYC and HER2 co-amplified." (PMID 35448150, 2022). "In fact, the MYC oncogene promotes overexpression of DNMT1, which results in tumor maintenance and progression in BL." (PMID 35326620, 2022). "Our findings demonstrate that the small-molecule MYCMI-7 binds MYC and inhibits interaction between MYC and MAX, thereby hampering MYC-driven tumor cell growth in culture and in vivo while sparing normal cells." (PMID 36874405, 2022). "While WRN is commonly regarded as a tumor suppressor, its pharmacological inhibition was proposed to achieve synthetic‐lethal effects in neoplastic cells characterized by high replication stress, which may render it effective also against MYC‐overexpressing cancer." (PMID 36214609, 2022).
tumor (continued). "We transfected MCF-7 human tumor cells with vectors with FLAG-tagged EsuDRG1 or HsaDRG1 and/or MYC-tagged EsuDFRP1 or HsaDFRP1 and analysed cell lysates by Western blot." (PMID 35790840, 2022). "Recent studies have shown that formononetin can inhibit PD-L1 expression by interfering with the interaction between MYC and STAT3, while enhancing the activity of CTLs and restoring their ability to kill tumor cells." (PMID 35463082, 2022). "Most human miRNAs function as tumor suppressors by directly targeting and inhibiting oncogenes, such as RAS and MYC." (PMID 35743145, 2022). "I-BET-762 is also well studied and was reported to reduce MYC expression in PRCA and subsequently inhibit cell growth and reduce the tumor burden." (PMID 35680563, 2022). "This was further evidenced by increased expression of c-MYC (V1), E2F and reactive oxygen species (ROS) pathway genes in KPP tumor cells." (PMID 35477555, 2022). "In particular, we show that miR-138 binds to the MYC CDS, inhibits MYC expression and suppresses tumor growth." (PMID 34937878, 2022). "Tumours showed robust downregulation of SWI/SNF targets and AR, ERG, MYC and Ki67 after five days of AU-15330 treatment, both when administered alone or with enzalutamide." (PMID 34937944, 2022). "Under hypoxia, we found that the glucose, fatty acid, and amino acid metabolism was upregulated; upregulated MYC targets and mTORC1 signaling pathway enhanced proliferation; downregulated PPAR promoted tumor migration." (PMID 36059442, 2022). "By upregulating c-MYC, cancers such as TNBC hijack these metabolic operations and promote unrestricted tumor growth and cell proliferation." (PMID 35642054, 2022). "Taken together, these analyses indicate that epigenetic mechanisms are deregulated in MYC RT in comparison to their COO, which is sustained by a subset of epigenetically-driven tumor cells." (PMID 35318328, 2022). "This multiple-microtissue transcriptome analysis revealed three cancer cell-type clusters in the primary tumor and axillary lymph node metastasis, two of which were cancer stem cell (CSC)-like clusters (CD44/MYC-high, HMGA1-high)." (PMID 35611554, 2022). "After a single intratumoral administration of CpG directly into MYC-ON tumors, we observed more MHC-I expression on the tumor cells." (PMID 35760778, 2022). "To further validate the effect of RAI14 on tumor growth, we detected Ki67, RAI14, FBXO32 and c-MYC by using immunohistochemistry." (PMID 36233342, 2022). "FOXC1 downstream targets, such as MYC, LINC01123, and MMP10, have been reported to regulate tumor progression in various cancer types." (PMID 35406487, 2022). "We also explored the changes in SUV and metabolic tumor volume (MTV) between baseline PET, I-PET, and EoT-PET scans for both MYC + and MYC- DLBCL patients." (PMID 34476551, 2022). "In PCa, the STAT protein family promotes tumor progression and mediates therapy resistance by regulating oncogene and pro-survival gene transcription (e.g., BCL2L1, MCL1, MYC, CCND1)." (PMID 35207527, 2022). "Moreover, elevation of FOXM1 message was associated with elevated expression of MYC and statistical comparison of paired baseline and progression samples from 65 patients revealed that FOXM1 underwent, on average, a ~2-fold upregulation during tumor progression." (PMID 35794249, 2022). "The findings presented here uncover a novel SOX2:MYC signaling axis that regulates tumor cell proliferation and demonstrate that SOX2 elevation decreases the expression of MYC and downregulates MYC target genes." (PMID 35454854, 2022). "The Mann–Whitney U test was used to compare the mRNA expression relationship between MYC and INTS14 or ERI2 in a dataset featuring each tumor type." (PMID 35887071, 2022). "TFs, such as XBP1, TAF7, ELF3, MYC, MAX, etc., were more enriched in tumor cells of luminal BC than the other two subtypes." (PMID 36077333, 2022).
tumor (continued). "Together, these data demonstrate MYC-ON tumors have low MHC-I expression and turning MYC off rescued MHC-I cell surface expression and concurrently increased CD8+ T-cell tumor infiltration." (PMID 35760778, 2022). "Of note, CDK16 knockdown led to a reduced expression of MYC proto‐oncogene, bHLH transcription factor (MYC) and CD274 molecule (PD‐L1), which in turn enhanced the tumor‐suppressive effects of senescent cancer cells." (PMID 34687270, 2022). "MYC specifically activates the expression of glutamine transporter and glutaminase in tumors, thereby regulating the reprogramming of glutamine metabolism in tumors.At the same time, MYC also regulates the expression of PD-L1 and CD47 in the tumor cells." (PMID 35897036, 2022). "By inhibiting c-MYC and RUNX2 expression, JQ1 decreased OB differentiation and tumour progression, suppressing c-MYC and RUNX2 expression." (PMID 35681577, 2022). "This study demonstrated a MYC–miR-105–MXI1–MYC loop that leads to miR-105-reprogramming in CAFs nourishing cancer cells with energy-rich metabolites and contributing to sustained tumor growth." (PMID 35955480, 2022). "This was further supported by the significant correlation between the levels of MYC mRNA/protein and the response to MYCMI-7 within the NCI-60 tumor cell line panel." (PMID 36874405, 2022). "Gene set enrichment analysis (GSEA) revealed a subpopulation of <0.6% primary tumor cells positively enriched for an EMT signature while negatively enriched for E2F and MYC targets, MTORC1 signaling, ER responses, oxidative phosphorylation, and glycolysis." (PMID 36008376, 2022). "To place this finding into context, we analyzed the correlation of MYC and PRMT5 mRNA expression across tumor entities." (PMID 35439169, 2022). "Genes located in this region, including MYC, POU5F1B and PVT1, were notorious for tumor progression." (PMID 35493106, 2022). "MYC and hypoxia-inducible factor 1 (HIF-1) reprogramming in malignant tissues allows them to better survive tumor microenvironmental alterations." (PMID 35204484, 2022). "The expression levels of MYC, NR5A2, SNAI1, TWIST1, and STK11 were significantly higher in tumor-adjacent tissues than in the matched EC samples, and this difference was not influenced by the content of cancer cells in cancer-adjacent tissues." (PMID 36140779, 2022). "Ultimately, they confirmed that MYC and MCL1 contribute to CSC enrichment and tumor-initiating capacity in TNBC." (PMID 36501221, 2022). "In murine tumor models, PIM kinases are weak oncogenes by themselves, but can exert strong cooperation with other oncogenes, in particular with MYC and MYCN in lymphomagenesis and prostate carcinogenesis." (PMID 36214609, 2022). "MYC (but also PVT1 at a lower level) is overexpressed in the two patients with HPV integration in the MYC/PVT1 region, as compared to the expression in the 42 other HNSCC tumours." (PMID 35398964, 2022). "We found that XBP1, TAF7, ELF3, MYC, MAX, etc., were more enriched in tumor cells of luminal BC than the other two subtypes." (PMID 36077333, 2022). "Mechanistically, BPTF is required for c-MYC recruitment to the promoter of ABC-transporters and its downregulation facilitates gemcitabine accumulation in tumour cells, increases DNA damage, and a generates a strong synergistic effect in vivo." (PMID 35326669, 2022). "The let-7 family is known for its tumor-suppressor activity (by inhibiting NRAS, HMG2A and MYC protooncogenes), and their reduced levels are typically associated with cancer stemness." (PMID 36010971, 2022). "Disease control was achieved for 32 weeks in one patient with a dual c-MYC and HER2 highly co-amplified tumour." (PMID 35448150, 2022).